BTK (Bruton tyrosine kinase)
Diseases named in the same sentence as BTK in open-access papers (continued):
Sharing a sentence is not in itself a finding about the gene and the disease.
X-linked agammaglobulinemia (165 papers, 2010 to 2026). X-linked agammaglobulinemia (XLA) is a clinically variable form of isolated agammaglobulinemia, an inherited immunodeficiency disorder (see this term), and is characterized in affected males by recurrent bacterial infections during infancy. "X-linked agammaglobulinemia (XLA) is an inborn error of immunity (IEI) caused by loss-of-function variants in the Bruton tyrosine kinase (BTK) gene, classically presenting in early childhood with recurrent bacterial infections." (PMID 42253969, 2026). "Splice-switching oligonucleotides (SSOs) targeting BTK pre-mRNA offer a potential therapy for X-linked agammaglobulinemia (XLA)." (PMID 40171248, 2025). "This study provides evidence that SSOs made from a rather unique collection of different chemistries are able to correct aberrantly spliced BTK in B lymphocytes using a mouse model of X-linked agammaglobulinemia." (PMID 40171248, 2025). "This inhibitory function of BTK is pivotal for understanding the spontaneous onset of colitis observed in patients with X-linked agammaglobulinemia who harbor BTK mutations." (PMID 40307577, 2025). "In humans, mutations in BTK can cause X-linked agammaglobulinemia (XLA), which affects B-cell and plasma cell levels in the blood." (PMID 40432438, 2025). "X-linked agammaglobulinemia (XLA) is an inborn error of immunity resulting from mutations in the BTK gene." (PMID 41327272, 2025). "X-linked agammaglobulinemia (XLA) is a rare primary immunodeficiency disorder caused by mutations in the Bruton tyrosine kinase (BTK) gene." (PMID 40895547, 2025). "Inactivating the human BTK gene results in X-linked agammaglobulinemia, an inherited immune disorder characterized by the absence of mature B lymphocytes and IG production." (PMID 40421329, 2025). "X-linked agammaglobulinemia (XLA) is a rare inborn error of immunity caused by loss-of-function mutations in the gene encoding Bruton’s tyrosine kinase (BTK)." (PMID 40917692, 2025). "Mutation of the BTK gene results in X-linked agammaglobulinemia (XLA) in humans, which is a rare immunodeficiency that prevents the development of mature B lymphocytes, leading to agammaglobulinemia." (PMID 40432438, 2025). "Initially, BTK was identified as a potential contributor to the pathogenesis of X-linked agammaglobulinemia, an inherited immunodeficiency disorder." (PMID 40235547, 2025). "X-linked agammaglobulinemia (XLA) is a congenital immunodeficiency disorder caused by mutations in the Bruton tyrosine kinase (BTK) gene, which encodes an essential protein required for the development and maturation of B cells." (PMID 40948744, 2025). "This was followed by variants in the BTK gene, associated with X-linked agammaglobulinemia, in four patients." (PMID 41190063, 2025). "X-linked agammaglobulinemia (XLA) is a rare primary immunodeficiency (PID) caused by pathogenic variants in the Bruton’s tyrosine kinase (BTK) gene, resulting in a profound defect in B cell maturation and subsequent agammaglobulinemia." (PMID 40963632, 2025). "In BTK, disease-linked loss-of-function mutations are associated with X-linked agammaglobulinemia (XLA)." (PMID 40613782, 2025). "We observed that a downregulating mutation in the PH-TH domain (R28H) linked to X-linked agammaglobulinemia impairs BTK activation at the membrane and in the cytosol by preventing PH-TH dimerization." (PMID 38971313, 2024). "X-linked agammaglobulinemia (XLA) is another primary immunodeficiency disease caused by mutations in the Bruton tyrosine kinase (BTK) gene." (PMID 38644403, 2024). "Originally identified through a mutation associated with X-linked agammaglobulinemia in human immunodeficiency, BTK is linked to inflammatory signaling." (PMID 39280007, 2024). "X-linked agammaglobulinemia (XLA) is an inborn error of immunity caused by mutations in the gene encoding Bruton’s tyrosine kinase (BTK)." (PMID 38676861, 2024).
X-linked agammaglobulinemia (continued). "BTK downregulation in patients with X-linked agammaglobulinemia (XLA) causes recurring bacterial and viral infections." (PMID 38971313, 2024). "We studied BTK-dependent fungal responses in neutrophils from diverse populations, including healthy donors, patients who were treated with BTKi, and X-linked agammaglobulinemia patients." (PMID 38696257, 2024). "X-linked agammaglobulinemia (XLA) is a primary immunodeficiency disease caused by mutations in the Bruton tyrosine kinase (BTK) gene." (PMID 38689221, 2024). "BTK is mutated in the X-linked agammaglobulinemia (XLA), a rare genetic disorder which was initially described in 1952." (PMID 39456530, 2024). "The role of BTK in BCR signaling was first studied in X-linked agammaglobulinemia (XLA), a B cell immunodeficiency characterized by an almost complete block of B cell development at the pre-B cell stage." (PMID 39518015, 2024). "Five different SNVs were identified in the BTK gene related to X-Linked Agammaglobulinemia (XLA; OMIM #300300) representing the most prevalent disorder in the cohort." (PMID 37592284, 2023). "BTKbase is an international database for disease-causing variants in Bruton tyrosine kinase (BTK) leading to X-linked agammaglobulinemia (XLA), a rare primary immunodeficiency of antibody production." (PMID 40225173, 2023). "X-linked agammaglobulinemia (XLA) is a genetic disorder with mutation in Bruton's tyrosine kinase (BTK)." (PMID 38046560, 2023). "Defects in the BTK genomic locus can lead to a primary immunodeficiency disorder known as X-linked agammaglobulinemia (XLA)." (PMID 37685940, 2023). "X-linked agammaglobulinemia (XLA) is a monogenic IEI caused by a loss-of-function mutation in Bruton’s tyrosine kinase (BTK) gene, and it is characterized by reduced mature B lymphocytes." (PMID 37051232, 2023). "The real impact of B cells on susceptibility for cryptococcosis has also been questioned as invasive fungal infections are very rare in patients with X-linked agammaglobulinemia with BTK deficiency, probably because of residual BTK activity in myeloid cells." (PMID 35425769, 2022). "Harmful variants in human BTK cause X-linked agammaglobulinemia (XLA), a primary immunodeficiency, in mouse X-linked immunodeficiency." (PMID 35782867, 2022). "The discovery of the Bruton tyrosine kinase (BTK) as the product of the defective gene in X-linked agammaglobulinemia goes back to almost thirty years ago." (PMID 35992808, 2022). "X-linked agammaglobulinemia (XLA) is mainly caused by a mutation of the Bruton’s tyrosine kinase (BTK) gene." (PMID 35159366, 2022). "BTK was first identified in the primary immunodeficiency disease X-linked agammaglobulinemia in humans, which is caused by a BTK gene mutation." (PMID 34443496, 2021). "About 85%–90% of patients in this group have X-linked agammaglobulinemia (XLA) due to mutations in the Bruton tyrosine kinase gene (BTK), and 5% of patients have immunoglobulin μ heavy chain deficiency." (PMID 33643318, 2021). "High-BTK expression in hematopoietic tissues plays a critical role in the differentiation of blood cells; especially, mutations in the BTK gene result in X-linked agammaglobulinemia in humans and X-linked immunodeficiency in mice." (PMID 33640903, 2021). "X-linked agammaglobulinemia (XLA) is an inherited immunodeficiency caused by mutations in the Bruton Tyrosine Kinase (BTK) gene." (PMID 34262886, 2021). "BTK was originally identified as the gene mutated in X-linked agammaglobulinemia (XLA) and was subsequently shown to be the rate-limiting step in B cell receptor signaling and B cell survival and differentiation." (PMID 35008785, 2021). "This variation prevents Bruton tyrosine kinase (BTK) expression and causes X-linked agammaglobulinemia (XLA)." (PMID 32951567, 2021). "Deficiency of Bruton’s tyrosine kinase (BTK), a cause of X-linked agammaglobulinemia (XLA), is sometimes associated with colonic inflammation." (PMID 33808793, 2021).
X-linked agammaglobulinemia (continued). "The sequence of the BTK gene was reported in 1993 by two independent research teams, as a result of a hunt for the genetic cause of X-linked agammaglobulinemia, XLA, and a search for novel tyrosine kinases." (PMID 34177947, 2021). "BTK plays an instrumental role in B-cell development as mutations in the BTK gene have been linked to the primary immunodeficiency X-linked agammaglobulinemia (XLA)." (PMID 34249912, 2021). "BTK was originally identified as the gene mutated in X-linked agammaglobulinemia (XLA) and was subsequently shown to be the rate-limiting step in B cell receptor signaling and autoreactive B cell survival and differentiation." (PMID 35008785, 2021). "In 1993, BTK was identified as the gene defective in X-linked agammaglobulinemia (XLA), an inherited immunodeficiency disease in humans characterized by a drastic deficiency in B lymphocytes, low levels of immunoglobulin (Ig), and recurring infections." (PMID 33818636, 2021). "The deficiency of BTK, known, for example, in the X-linked agammaglobulinemia disease, leads to very low levels of circulating Igs due to a lack of functional B cells." (PMID 33880738, 2021). "BTK mutations cause X-linked agammaglobulinemia type 1, which is associated with a failure of Ig heavy chain rearrangement." (PMID 34440129, 2021). "Correlates of BTK inhibition can be derived from the well-known syndrome of X-linked (Bruton) agammaglobulinemia, which is caused by mutation of the BTK gene." (PMID 34947040, 2021). "X-linked agammaglobulinemia (XLA) is a rare genetic disease caused by a mutation in the Bruton tyrosine kinase (BTK) gene." (PMID 33235662, 2020). "Mutations along the BTK gene BTK cause X-linked agammaglobulinemia (XLA), characterized by severe defects of the B-cell development and the innate immune system." (PMID 32146518, 2020). "X-linked Agammaglobulinemia (XLA) is a primary immunodeficiency disease caused by a mutation in the Bruton Tyrosine Kinase (BTK) gene that encodes an essential protein involved in B-cell maturation." (PMID 33224144, 2020). "X-linked agammaglobulinemia (XLA) is an X-linked inherited disease caused by genetic mutations in the Bruton tyrosine kinase (BTK) gene, which suppress the development of mature B lymphocytes." (PMID 31510946, 2019). "Individuals with X-linked agammaglobulinemia (XLA) have a mutation in the gene that is responsible for Bruton tyrosine kinase (BTK), which involves a failure in antibody production and a high susceptibility to bacterial infections." (PMID 31338088, 2019). "X-linked agammaglobulinemia (XLA) is an immunodeficiency disease caused by mutations in the gene coding for BTK, leading to failure to produce mature B lymphocytes." (PMID 31830942, 2019). "X-linked agammaglobulinemia (XLA) is a primary immunodeficiency disorder caused by germline mutations in the Bruton tyrosine kinase (BTK) gene on X chromosome." (PMID 31510946, 2019). "The majority of patients are boys suffering from X-linked agammaglobulinemia (XLA) as a result of mutations in the gene encoding Bruton's tyrosine kinase (BTK), an enzyme pivotal in the development of B cells." (PMID 31803177, 2019). "The importance of BTK is evidenced by the fact that a BTK loss-of-function mutation is responsible for X-linked agammaglobulinemia (XLA), which is characterized by deficiency of mature B-cells and antibody production." (PMID 29861875, 2018). "Most of these individuals suffer from X-linked agammaglobulinemia (XLA) which occurs due to mutations in the gene encoding Bruton’s tyrosine kinase (BTK), an enzyme essential for B-cell development." (PMID 29867917, 2018). "X-linked agammaglobulinemia (XLA) is a primary immunodeficiency caused by Bruton’s tyrosine kinase (BTK) mutation." (PMID 30147693, 2018). "BTK was initially shown to be mutated in the primary immunodeficiency X-linked agammaglobulinemia (XLA) and is essential at various stages of B lymphocyte development." (PMID 29455639, 2018).
X-linked agammaglobulinemia (continued). "X-linked agammaglobulinemia (XLA) is a primary immunodeficiency caused by mutations of Bruton’s tyrosine kinase (BTK)." (PMID 30147693, 2018). "BTK was initially shown to be defective in the primary immunodeficiency X-linked agammaglobulinemia (XLA) and is essential both for B cell development and function of mature B cells." (PMID 29455639, 2018). "Mutations in the BTK gene were shown to cause X-linked agammaglobulinemia (XLA) in humans and X-linked immunodeficiency (Xid) in mice." (PMID 29320389, 2018). "X-linked agammaglobulinemia (XLA) is a symptomatic primary antibody deficiency (PAD) caused by mutations in the Bruton’s tyrosine kinase (BTK) gene located on the long arm of X-chromosome encoding the cytoplasmic BTK." (PMID 28422989, 2017). "Mutations in the human BTK gene are responsible for X-linked agammaglobulinemia (XLA), a male immunodeficiency that causes shortage of mature B cells and serum immunoglobulin." (PMID 28361711, 2017). "Four patients had mutations in the Bruton tyrosine kinase gene, and a final diagnosis of X-linked agammaglobulinemia was established." (PMID 27648512, 2016). "X-linked agammaglobulinemia (XLA) is a congenital immunodeficiency caused by mutations in Bruton’s tyrosine kinase (BTK)." (PMID 26873735, 2016). "In humans, mutations in the BTK gene is characterized by a B-lymphocyte developmental defect, giving rise to a primary immunodeficiency disease called X-linked agammaglobulinemia (XLA)." (PMID 26784025, 2016). "Mutations in the Bruton agammaglobulinemia tyrosine kinase (BTK) gene are responsible for X-linked agammaglobulinemia (XLA)." (PMID 26417435, 2015). "X-linked agammaglobulinemia (XLA) is a primary immunodeficiency disease caused by mutations in the gene coding for Bruton’s tyrosine kinase (BTK)." (PMID 25638286, 2015). "X-linked agammaglobulinemia (XLA) is a primary immunodeficiency disease that is caused by mutations in the Bruton’s tyrosine kinase (BTK) gene." (PMID 25316352, 2014). "Mutations in BTK are known to lead to X-linked agammaglobulinemia (XLA) in humans and X-linked immunodeficiency (xid) in mice." (PMID 25170774, 2014). "The central role of BTK in B cell function is underscored by the human disease X-linked agammaglobulinemia, which is caused by the loss of function mutations in BTK." (PMID 24433470, 2013). "X-linked agammaglobulinemia is a hereditary immunodeficiency caused by mutations in the gene encoding BTK and is characterized by recurrent severe infections." (PMID 23424595, 2013). "Mutations in BTK block B cell maturation at the pre B cell stage and cause X linked agammaglobulinemia (Bruton s agammaglobulinemia), an immunodeficiency disorder characterized by the virtual absence of B cells and recurrent bacterial infections." (PMID 23170196, 2012). "Bruton agammaglobulinemia is a primary immunodeficiency caused by the existence of mutations inthe gene that encodes Bruton tyrosine kinase (BTK) on chromosome X. Approximately one third ofthe mutations are at sites CGG, which encodes for arginine." (PMID 20302197, 2010). "X-linked agammaglobulinemia, which arises due to Bruton’s tyrosine kinase (BTK) mutations in genes important for B cell development, is less frequently associated with colitis compared to CVID subsets and is characterized by less severe immunoglobulin deficiency." (PMID 40649913, 2025). "Pathogenic variants of BTK are causes of X-linked agammaglobulinemia, also known as Bruton disease." (PMID 37325673, 2023). "BTK gene mutation leads to human X-linked agammaglobulinemia and mouse X-linked immunodeficiency." (PMID 37638060, 2023). "Bruton’s tyrosine kinase (BTK) was firstly reported to be related to the inherited immunodeficiency disease x-linked agammaglobulinemia (XLA) in 1993, mutations of which cause a disorder in the transformation of pre-B cells in the bone marrow into mature peripheral B cells." (PMID 36183125, 2022).
X-linked agammaglobulinemia (continued). "Mutations affecting the BTK gene lead to a disease called X-linked agammaglobulinemia (XLA)." (PMID 34645618, 2021). "Mutations in the BTK gene in humans cause X-linked agammaglobulinemia (XLA), which is a primary humoral immunodeficiency characterized by an arrest in the B-cell development, at the transition between the pro-B to the pre-B cell stage, with almost total lack of immunoglobulin production." (PMID 33777941, 2021). "However, aberrant BTK signaling has been recognized in diseases, like X-linked agammaglobulinemia (XLA), as well as various B cell lymphomas." (PMID 34063667, 2021). "Therefore, impaired BTK function has been associated with primary immunodeficiencies such as X-linked agammaglobulinemia (XLA), whereas its upregulation underlies several B-cell malignancies, such as chronic lymphocytic leukaemia (CLL) or autoimmune diseases." (PMID 33322571, 2020). "Sequencing of the BTK coding regions revealed a point mutation, hemizygous c.1349 + 5G > A, which is an intron mutation and has been previously reported to be responsible for X-linked agammaglobulinemia." (PMID 31830942, 2019). "Patients with loss-of-function mutations in the BTK gene present with X-Linked agammaglobulinemia (XLA), an inherited immunodeficiency marked by an almost complete arrest of B cell development at the pre-B cell stage in the BM and a near absence of peripheral B cells and circulating Ig." (PMID 30761150, 2019). "BTK mutation in humans results in X-linked agammaglobulinemia." (PMID 28416773, 2017). "Functional disrupting mutations of BTK lead to X-linked agammaglobulinemia (XLA) in humans and X-linked immunodeficiency (Xid) in mice, primary immunodeficiency diseases which are characterized by lack of mature B cells and plasma cells and low levels of immunoglobulins." (PMID 28915637, 2017). "X-linked agammaglobulinemia (XLA) is an X-linked inherited disease caused by a germline mutation in the BTK gene leading to Bruton’s tyrosine kinase deficiency, which results in the impaired development of B-lymphocytes and a subsequent lack of immunoglobulin production." (PMID 27722150, 2016). "This approach was employed to alter the binding and cleavage specificity of the I-Anil LHE to recognize a mutation in the mouse Bruton tyrosine kinase (Btk) gene causative for mouse X-linked immunodeficiency (XID)—a model of human X-linked agammaglobulinemia (XLA)." (PMID 24682825, 2014). "Interestingly, in BTK, homologous mutations have been reported to cause X-linked agammaglobulinemia and the observed mutations in our eight patients have mutations in corresponding BTK residues indicating similar structural alterations." (PMID 25339095, 2014). "In mammalian cells, there is a single transcript splice-form and the corresponding Btk-protein plays an important role for B-lymphocyte development with alterations within the human BTK gene causing the immunodeficiency disease X-linked agammaglobulinemia in man and a related disorder in mice." (PMID 22574122, 2012). "Here, the activity of several different SSOs was investigated as potential treatments for B lymphocyte disorders with a focus on X-linked agammaglobulinemia (XLA), caused by defects in the gene encoding Bruton's tyrosine kinase (BTK)." (PMID 40171248, 2025). "Though cumulative safety data for next-generation BTKis have been positive, clinicians’ safety concerns for pharmacologic BTK inhibitors may still be overshadowed by knowledge of the severe phenotype of congenital BTK deficiency, otherwise known as X-linked agammaglobulinemia (XLA)." (PMID 38492772, 2024). "Of these, 6 patients had common variable immunodeficiency (CVID), 3 had X-linked agammaglobulinemia (XLA) due to loss-of-function mutations in the Bruton tyrosine kinase (BTK), and 1 patient had autosomal recessive agammaglobulinemia (ARA), the etiology of which is unknown." (PMID 33173418, 2020).